YTHDF3 (YTH N6-methyladenosine RNA binding protein F3)
Diseases named in the same sentence as YTHDF3 in open-access papers (continued):
Sharing a sentence is not in itself a finding about the gene and the disease.
tumor (continued). "To investigate the relationship between YTHDF3 and glucose metabolism in HCC, we detected pyruvate and lactate levels of tumor tissue and plasma from chemically induced hepatocarcinogenesis mice." (PMID 36471428, 2022). "All 39 paired samples were used for expression validation of YTHDF1 and YTHDF3, and the results revealed that YTHDF1 and YTHDF3 had higher expression in 32 and 30 tumor samples compared to the corresponding adjacent tissue, respectively." (PMID 34804948, 2021). "The tumor cells exhibited a significant increase in the expression of WTAP, YTHDF2, and YTHDF3, but a reduction in the expression of FTO and ALKBH5 compared to the normal epithelial cells in the para-tumor samples." (PMID 34733841, 2021). "YTH domain proteins, including YTHDF1, YTHDF2, YTHDF3, YTDHDC1 and YTHDC2, are the most reported m6A readers and promote the degradation of m6A modified mRNA and tumor progression." (PMID 34295828, 2021). "In recent years, increasing studies have confirmed that m6A methylation‐related genes, such as ALKBH5, FHL2, DGCR8, YTHDF2, YTHDF3, and PICM8, were overexpressed in tumor tissues and closely related to malignant tumors." (PMID 33264518, 2021). "Specifically, HNRNPC, YTHDF1, YTHDF2, METTL3, RBM15, YTHDF3, and KIAA1429 are highly expressed in tumor tissues." (PMID 32258108, 2020). "With TCGA cohort, we examined the four common m6A readers (YTHDF1, YTHDF2, YTHDF3, and YTHDC1) in LUAD tumor samples and normal samples, and found YTHDF1 highly expressed in tumor tissues." (PMID 32195181, 2020). "Five m6A-related genes (ZC3H13, METTL14, YTHDF2, YTHDF3 and HNRNPA2B1) showed significantly downregulated in tumor tissue, while seven regulators (YTHDC2, FTO, WTAP, METTL3, ALKBH5, RBM15 and KIAA1429) was remarkably upregulated in ccRCC." (PMID 32419773, 2020). "Most metastatic tumor samples showed strong VIRMA and YTHDF3 immunoexpression intensity, while weak/moderate staining was observed for m6A." (PMID 30866959, 2019). "Considering all tumor samples, VIRMA and YTHDF3 mRNA expression levels were positively correlated (rs = 0.44, p < 0.001)." (PMID 30866959, 2019). "Ultimately, we established a key role of YTHDF3 in m6A-modified GAS5 and degradation of GAS5 transcription, uncovering a negative feedback loop between YAP-interacting lncRNA GAS5 and the m6A reader YTHDF3 in Hippo/YAP signaling and tumor progression of CRC." (PMID 31619268, 2019). "In this tumor model, a positive strong correlation between VIRMA and the reader YTHDF3 was also observed, supporting again a cooperation between these two players for establishing m6A modification in urologic tumors." (PMID 30428628, 2018). "Importantly, Ythdf3 ablation substantially attenuated HPV viral burden, impairing viral persistence within the tumor niche." (PMID 41453852, 2025). "YTHDF3 translates m6A-rich transcripts and promotes brain metastasis of tumors; FTO regulates the stability and expression of PPARγ and C/EBP-α/β mRNA, and promotes tumor growth and lung metastasis." (PMID 41446042, 2025). "Consequently, decreased YTHDF3 levels in NPC lead to increased CBX1 expression, promoting tumor progression." (PMID 39695216, 2024). "In NPC, YTHDF3 destabilizes m6A-modified CBX1 mRNA, acting as a tumor suppressor." (PMID 39695216, 2024). "The mRNA expression levels of YTHDC2, YTHDF1, YTHDF3, IGF2BP1, and IGF2BP3 were significantly increased in tumour tissues compared with paired normal breast tissues, while the METTL14, WTAP, FTO, and IGF2BP2 expression levels were significantly decreased in tumour tissues." (PMID 36632454, 2023). "In addition, METTL3, YTHDF3 and IGF2BP3 affect tumor angiogenesis by regulating the expression of VEGF." (PMID 38053093, 2023). "TRMT61A, TRMT61B, YTHDF1 and YTHDF3 mRNAs were higher in tumor tissues, but protein expression was weaker or not apparently distinct between tumor and normal samples." (PMID 34777359, 2021).
tumor (continued). "Besides, the expression of KDM5B, miR‐448, YTHDF3 and ITGA6 in mouse tumour tissues was measured by RT‐qPCR; the results revealed that up‐regulation of KDM5B reduced miR‐448 expression, while up‐regulating KDM5B, YTHDF3 and ITGA6 expression." (PMID 33829656, 2021). "Collectively, KDM5B could activate the YTHDF3/ITGA6 pathway to enhance the proliferation and growth of tumour cells by inhibiting the expression of miR‐448 in HCC, eventually leading to the occurrence of HCC." (PMID 33829656, 2021). "We suggest that the ubiquitin-mediated proteolysis affected by YTHDF3 and YTHDC2 may play a crucial role in tumor progression." (PMID 32596399, 2020). "This study suggests a promising KDM5B‐targeted therapy for HCC patients and also proposes that a KDM5B/miR‐448/YTHDF3/ITGA6 axis is involved in the occurrence and development of this cancer, which could constitute an important tumour‐related molecular mechanism." (PMID 33829656, 2021). "However, translation driven by m6A requires an m6A reader such as YTHDF3 in the microenvironment, whereas the expression of circRNAs might not substantially differ between tumor tissue and adjacent normal tissue." (PMID 35157402, 2022). "Among the six cuproptosis-related lncRNAs, YTHDF3.AS1 has not been previously reported, whereas the other five lncRNAs have been reported to affect tumor prognosis." (PMID 37529698, 2023). "By comparing the expression of m6A related gene in the tumor group and the normal group (METTL14, YTHDF2 and YTHDF3 could not be excluded with statistical significance), mutation rates of m6A gene were all greater than 0, which could not be excluded." (PMID 37194014, 2023).
cancer (60 papers, 2019 to 2026). A tumor composed of atypical neoplastic, often pleomorphic cells that invade other tissues. "We discovered that FAM110B expression often showed a favorable correlation with pan-cancer gene expression associated with m1A, m5C, and m6A, particularly in YTHDF3, YTHDC1, NSUN3, TET2, and METTL14." (PMID 39170745, 2024). "Simultaneously, YTHDF3 CNV was linked to poor OS in the following cancers: UVM (P = 0.00016), UCEC (P = 0.0015), KIRC (P = 0.04), and KIRP (P = 0.00014)." (PMID 36606187, 2022). "To assess the diagnostic value of YTHDF3, we plotted ROC curves and calculated the AUCs for various cancers." (PMID 36606187, 2022). "YTHDF3 SNV was linked to poor OS in the following cancers: BRCA (P = 0.0011), OV (P = 0.028), LUAD (P = 0.00064), and COAD (P = 0.036) from the TCGA database." (PMID 36606187, 2022). "Here, we show the potential relationship between cancer-associated fibroblasts and YTHDF3 gene expression in the “TIDE”, “MCPCOUNTER”, and “EPIC” databases." (PMID 36606187, 2022). "These conclusions indicate that YTHDF3 is abnormally expressed in cancer tissues and has potential diagnostic value." (PMID 36606187, 2022). "To explore this, we examined the associations between immune checkpoint genes and YTHDF3 expression across cancer." (PMID 36606187, 2022). "YTHDF3 CNV was linked to poor DSS in the following cancers: UVM (P = 0.00014), UCEC (P = 0.0019), KIRC (P = 0.0017), KIRP (P = 4.3 x 10-5), THYM (P = 0.0028), and THCA (P = 0.013)." (PMID 36606187, 2022). "We further explored progress-free survival (PFS), and interestingly, we found that YTHDF1/2 was a risk factor for cancer progress in KICH, LIHC and PRAD, while YTHDF3 was a risk factor for cancer progress in KICH and KIRP, and a protective factor in KIRC and LUSC." (PMID 37833468, 2023). "In addition, our findings are the first to suggest that a relationship exists between YTHDF3 expression and immune invasion levels of cancer-associated fibroblasts across cancers." (PMID 36606187, 2022). "Our data suggest that YTHDF3 has good diagnostic value in these 12 cancer types." (PMID 36606187, 2022). "The ROC analysis suggested that YTHDF3 has high diagnostic value in 13 types of cancer." (PMID 36606187, 2022). "Interestingly, in clinical patients of HCC, q-PCR and Western blot results of fresh surrounding and carcinoma tissues indicated that high expressions of PFKL were largely associated with high expressions of YTHDF3 at both mRNA and protein levels." (PMID 36471428, 2022). "Additionally, highly expressed YTHDF3 was linked to poor PFI in the following cancers: BRCA (HR = 1.44, P = 0.031), CESC (HR = 3.50, P = 0.001), UVM (HR = 3.09, P = 0.008), KICH (HR = 4.03, P = 0.025), PAAD (HR = 1.61, P = 0.019), GBMLGG (HR = 1.42, P = 0.001), and UCEC (HR = 1.46, P = 0.029)." (PMID 36606187, 2022). "Furthermore, our study found that YTHDF3 expression is related to various disease stages and patient ages, prompting us to use TCGA database to draw ROC curves and assess the diagnostic value of YTHDF3 in these cancer types." (PMID 36606187, 2022). "The finding that m6A readers, in this case YTHDF3, are important for aggressive GC behavior supports the targeting of RNA modifications as a new and promising cancer therapeutic avenue." (PMID 40366509, 2025). "Given the integral role of interferons in antitumor immunity, understanding the impact of YTHDF3 on this pathway is crucial to elucidate its potential role in cancer immunology." (PMID 41453852, 2025). "YTHDF3, an m6A reader protein, is known to contributes to the development and progression of various cancers including GC." (PMID 40567896, 2025). "In the enrolled cancer samples, YTHDF3 highly expressed in NSCLC tissue as comparing with normal tissue." (PMID 38992016, 2024).
cancer (continued). "For instance, YTHDF3 has the dual role of oncogenic and tumor suppressor in different cancers and future studies should uncover if an upstream mediator determines the exact function of this m6A reader in a cell." (PMID 38075202, 2024). "For example, a recent study showed that the collaboration of a set of WERs of m6A (‘writer: METTL14’, ‘eraser: ALKBH5’ and ‘reader: YTHDF3’) regulates cancer growth and progression." (PMID 36300630, 2023). "Taken together, these results demonstrate that YTHDF3 expression is closely related to prognosis in various cancer types." (PMID 36606187, 2022). "Herein, we demonstrated that YTHDF3 is a potential prognostic pan-cancer biomarker using diverse bioinformatic tools." (PMID 36606187, 2022). "Although numerous studies have investigated m6A methylation-related genes, to the best of our knowledge, none have examined the expression patterns of YTH N6-methyladenosine RNA binding protein 3 (YTHDF3) across cancers." (PMID 36606187, 2022). "Previous studies have shown that YTHDF3 plays an important role in the occurrence and development in many types of cancer." (PMID 36606187, 2022). "To identify the molecular pathways enriched for YTHDF3, we examined activated signaling pathways across cancers by GSEA." (PMID 36606187, 2022). "Our results suggest that a significant correlation exists between high YTHDF3 expression and poor prognosis across cancers." (PMID 36606187, 2022). "The AUC of YTHDF3 in each cancer type was 0.926 (LAML), 0.922 (GBMLGG), 0.910 (CHOL), 0.950 (PAAD), 0.916 (LGG), 0.946 (GBM), 0.797 (STAD), 0.761 (LIHC), 0.789 (UCEC), 0.726 (ESCA), 0.726 (HNSC), and 0.717 (TGCT)." (PMID 36606187, 2022). "We examined YTHDF3 protein expression levels in 13 different cell lines, including normal and cancer cells, by WB analysis." (PMID 36606187, 2022). "Overall, we have shown in this study that YTHDF3 expression, immune cell infiltration, and prognosis are closely related in human cancers." (PMID 36606187, 2022). "This study provides the first comprehensive pan-cancer report on YTHDF3 and increases our understanding of its oncogenic role in different tumors." (PMID 36606187, 2022). "In the first step of our research, we used the TCGA database to determine the YTHDF3 expression levels in cancer and normal tissues." (PMID 36606187, 2022). "The results showed strong diffuse YTHDF3 expression in the cytoplasm of cell lines (H1299, H441, and H1975), suggesting that YTHDF3 is expressed in the cytoplasm of cancer cells." (PMID 36606187, 2022). "Additional experiments are necessary to demonstrate the potential function of YTHDF3 in cancer, which can increase the credibility of our results." (PMID 36606187, 2022). "We found YTHDF3 expression was greatly upregulated in carcinoma tissues and it was correlated with poor prognosis of HCC patients." (PMID 36471428, 2022). "Clinically, YTHDF3 was overexpressed in carcinoma tissues among HCC patients and higher expression of YTHDF3 was correlated with poor prognosis of HCC patients." (PMID 36471428, 2022). "We found protein expression of YTHDF3 in carcinoma tissues was greatly higher than that in normal counterpart surrounding tissues." (PMID 36471428, 2022). "Meanwhile, there was a positive correlation between serum AFP level and the expression of YTHDF3 in carcinoma tissue (r = 0.258, P < 0.0001)." (PMID 36471428, 2022). "Expression levels of YTHDF3 in carcinoma and surrounding tissues of HCC patients were evaluated by immunohistochemistry." (PMID 36471428, 2022). "Meanwhile, Western blot and qPCR assays showed that expressions of YTHDF3 in carcinoma tissues were greatly higher than those in normal counterpart surrounding tissues at both mRNA and protein levels." (PMID 36471428, 2022). "Studies have revealed that METTL14 and ALKBH5 control the expression of each other and inhibit the expression of YTHDF3, thereby blocking RNA demethylation to degrade cancer cells." (PMID 33628845, 2021).
cancer (continued). "Meanwhile, univariate and multivariate analyses showed that the increased expression of YTHDF3 was an independent predictor of cancer overall survival in patients with BRC." (PMID 31632489, 2019). "YTHDF3 is of significance in promoting the translation of oncogenic genes within diverse cancers." (PMID 40675967, 2025). "Additionally, YTHDF3 has been identified as a promoter of cancer cell-astrocyte interaction, thereby facilitating angiogenesis." (PMID 38408075, 2024). "Additionally, the CPTAC database contains the protein expression of YTHDF3 in only relatively few cancer types." (PMID 36606187, 2022). "However, the epigenetic mechanisms and biological functions of YTHDF3 in the pathogenesis of different cancers have been less well studied." (PMID 36606187, 2022). "The WB analysis suggested that YTHDF3 is highly expressed in most cancer cell lines." (PMID 36606187, 2022). "The YTHDF3 expression was significantly highly upregulated in 1,098 BC patients versus 292 normal group individuals (p < 0.001), as well as in 21 of the 27 analyzed cancer types." (PMID 35755811, 2022). "YTHDF3 could be a prognostic pan-cancer biomarker, and these findings deserve further investigation." (PMID 36606187, 2022). "Additionally, the results of the immune analysis using TIMER showed that high YTHDF3 expression levels in pan-cancer tissues were related to an immunosuppressive microenvironment." (PMID 36606187, 2022). "The results show that YTHDF3 expression is significantly different in various immune subtypes in most types of cancer, which could demonstrate that YTHDF3 is a promising cancer diagnostic biomarker that participates in immune regulation." (PMID 36606187, 2022). "A recent study showed that the YTHDF3 copy number increase in LIHC was significantly higher than in other cancers 33, where it was amplified by more than 6% 38, suggesting that YTHDF3 may be an important oncogene that is selected during cancer evolution." (PMID 36606187, 2022). "We first explored the relevance of YTHDF3 in pan-cancer and immune cells." (PMID 36606187, 2022). "Thus, it is important to accumulate the evidence indicating the common or diverse function of YTHDF3 in the malignant progression of cancer including EMT." (PMID 36183833, 2022). "Finally, we experimentally demonstrated that both overexpression and downregulation of YTHDF3 can affect cancer cell proliferation rates." (PMID 36606187, 2022). "We aimed to analyze the role of YTHDF3 from a pan-cancer perspective." (PMID 36606187, 2022). "First, the expression levels of YTHDF3 in the pan-cancer data from TCGA and GTEx were evaluated." (PMID 36606187, 2022). "Interestingly, when we divided HCC patients into YTHDF3 low-expression group and YTHDF3 high-expression group according to IHC staining scores of carcinoma tissue, we found that serum AFP level was significantly elevated in YTHDF3 high-expression group." (PMID 36471428, 2022). "Therefore, we speculated that high expression of YTHDF3 in most cancers has prognostic significance." (PMID 36606187, 2022). "Furthermore, these data suggest that YTHDF3 is involved in cancer cells proliferation and that YTHDF3-high cells may have a proliferative advantage." (PMID 36606187, 2022). "Notably, there was a negative correlation between immune immersion in cancer-associated fibroblasts and YTHDF3 expression in TGCTs (n = 150)." (PMID 36606187, 2022). "Interestingly, the reader gene YTHDF3 showed higher frequency of CNV events in all three cancers." (PMID 34804948, 2021). "The MIDN level was correlated with several immune checkpoint genes, such as VEGFA, and RNA modification genes such as YTHDF1, YTHDF2, YTHDF3, and YTHDC1 in cancers." (PMID 40002690, 2025). "Positive correlations between the expression of YTHDF3, YTHDF2, YTHDF1, and YTHDC1 and MIDN levels were detected in nearly all cancers." (PMID 40002690, 2025).